FOXN4 (forkhead box N4)
Description:
Transcription factor essential for neural and some non-neural tissues development, such as retina and lung respectively. Binds to an 11-bp consensus sequence containing the invariant tetranucleotide 5'-ACGC-3'. During development of the central nervous system, is required to specify the amacrine and horizontal cell fates from multipotent retinal progenitors while suppressing the alternative photoreceptor cell fates through activating DLL4-NOTCH signaling. Also acts synergistically with ASCL1/MASH1 to activate DLL4-NOTCH signaling and drive commitment of p2 progenitors to the V2b interneuron fates during spinal cord neurogenesis. In development of non-neural tissues, plays an essential role in the specification of the atrioventricular canal and is indirectly required for patterning the distal airway during lung development (By similarity).
Tractability: PROTAC: ubiquitination databases record sites on it.
Gene: Protein-coding gene on chromosome 12 (109,277,978 to 109,309,284, reverse strand). Ensembl gene ENSG00000139445.
Subcellular location: Nucleus
Subcellular location (Human Protein Atlas): Mitochondria; Nucleoplasm; Cytosol
Gene Ontology:
Molecular function: cis-regulatory region sequence-specific DNA binding; protein binding; chromatin binding; DNA-binding transcription factor activity; DNA-binding transcription factor activity, RNA polymerase II-specific; sequence-specific DNA binding
Biological process: amacrine cell differentiation; atrioventricular canal development; heart looping; positive regulation of transcription by RNA polymerase II; regulation of DNA-templated transcription; regulation of heart contraction; retina layer formation; ventral spinal cord interneuron differentiation; ventral spinal cord interneuron fate commitment
Cellular component: chromatin; nucleus
Genetic constraint (gnomAD): Loss-of-function variants: 11 observed, 41.88 expected, observed/expected ratio (o/e) 0.26, 90% interval 0.16 to 0.44. The upper end of that interval is the gene's LOEUF score, 0.44, which puts it in group 1 of 6, group 1 being the genes least tolerant of losing a copy. Missense variants: 553 observed, 683.37 expected, observed/expected ratio (o/e) 0.81, 90% interval 0.75 to 0.87. Synonymous variants: 294 observed, 290.63 expected, observed/expected ratio (o/e) 1.01, 90% interval 0.92 to 1.11.
Homologues: Orthologues: chimpanzee FOXN4 (99% identical), macaque FOXN4 (99% identical), dog FOXN4 (90% identical), guinea pig FOXN4 (85% identical), rabbit FOXN4 (84% identical), rat Foxn4 (82% identical), mouse Foxn4 (81% identical), tropical clawed frog foxn4 (61% identical), zebrafish foxn4 (56% identical). Paralogues in human: FOXN3 (21% identical), FOXN2 (19% identical).
Diseases named in the same sentence as FOXN4 in open-access papers:
FOXN4 is named in the same sentence as 11 diseases in open-access papers, as found by Europe PMC text mining. Sharing a sentence is not in itself a finding about the gene and the disease. The quoted sentences say what the papers report.
COVID-19 (5 papers, 2021 to 2023). A disease caused by infection with severe acute respiratory syndrome coronavirus 2. "The results showed that FUBP1 and RAB2A are expressed in several types of nasopharyngeal epithelial cells, including FOXN4+ cells, squamous cells, ciliated cells, and secretory cells, in the upper respiratory tract of COVID-19 patients, especially the vRNA+ group." (PMID 37932299, 2023).
prostate carcinoma (2 papers, 2008 to 2022). A carcinoma that arises from epithelial cells of the prostate gland. "A prognostic model composed of seven protein-coding genes (FOXN4, MGAM, MMP26, ARC, SOX11, PRAME, and VWA5B2) was established, and it was strongly associated with biochemical recurrence following radical prostatectomy in prostate cancer." (PMID 37255653, 2022). "For example, most prostate and colon cancer cell lines showed hypermethylation at FOXN4 and GALR2, but primary prostate cancers showed lower frequency methylation compared to primary colon cancer." (PMID 18446232, 2008). "Compared to adjacent normal prostate, all 8 genes had significantly higher methylation in prostate cancer by t-test analysis (P<0.001 for NKX2-5; P<0.001 for SPOCK2; P = 0.004 for GALR2; P<0.001 for CLSTN1; P<0.001 for NSE1; P<0.001 for DPYS; P = 0.019 for FOXN4; P<0.001 for SLC16A12)." (PMID 18446232, 2008).
breast carcinoma (1 paper, 2024). "The 12 protein-coding genes upregulated in positive margin group included several well-known tumor markers for breast cancer (EEF1A2, EPHA6, FOXN4, SOX15)." (PMID 38038766, 2024).
colon cancer (1 paper, 2008). "In a panel of 20 colon cancer cases, all these genes except IRX5, TFAP2E and TFAP2C showed significantly higher methylation in cancer by t-test analysis (P<0.001 for NKX2-5, DPYS SPOCK2, GALR2 and SLC16A12; P = 0.008 for FOXN4)." (PMID 18446232, 2008).
cancer (4 papers, 2008 to 2025). A tumor composed of atypical neoplastic, often pleomorphic cells that invade other tissues. "As FOXN4 has been reported to inhibit cancer progression, downstream pathways in LUAD were analyzed using the TCGA datasets." (PMID 40352924, 2025). "By participating in a FOXN4/TGF-β feedback signaling loop, miR-941 plays an oncogenic role in the process of TANs enhancing cancer cell malignant behavior." (PMID 40352924, 2025). "We also found that Cancer Cells interact with ITGB1 expressed in Fibroblasts, Endothelial Cells, SLC16A7 + Cells, FOXN4 + Cells, Basal Cells, GMP Cells, Monocytes, and NKT Cells through angiogenic signal molecules (VEGFA), which may stimulate tumor growth and metastasis." (PMID 36401283, 2022).
tumor (4 papers, 2022 to 2025). "The IHC of FOXN4 on mice tumor tissue presented the lower expression of FOXN4 with the treatment of the miR-941 mimic." (PMID 40352924, 2025). "In the Gbl13 sample (5 p), SLC16A7+ (or mesenchymal-like) cells and FOXN4+ cells were the major subpopulations of tumor cells, while neuronal cells and astrocytes were missing." (PMID 39126040, 2024). "For instance, systemic delivery of miR-941 inhibitors via lipid nanoparticles could suppress its activity in TANs and tumor cells, thereby disrupting the miR-941/FOXN4/TGF-β feedback loop." (PMID 40352924, 2025). "Hence, we speculated that the miR-941/FOXN4/TGF-β axis induces N2 polarization of neutrophils and enhances tumor progression of LUAD." (PMID 40352924, 2025). "Additionally, blocking miR-941 transfer from TANs to tumor cells could be achieved through exosome-mediated strategies, such as using exosomal inhibitors (e.g., GW4869) or engineering exosomes to deliver FOXN4 mRNA or TGF-β pathway antagonists." (PMID 40352924, 2025).
infection (1 paper, 2024). The state of being infected such as from the introduction of a foreign agent such as serum, vaccine, antigenic substance or organism. "Through the integrated analysis of miRNA-mRNA expression profiles, it was found that the expression of FOXN4, MUC4, KLK1 and CD163 were up-regulated under the action of miR-106b-3p after infection." (PMID 38178220, 2024).
FOXN4 also shares sentences with these, for which no sentence is quoted: lung adenocarcinoma (1 paper); nasopharyngeal carcinoma (1); neurodegenerative disease (1); Retinal dysplasia (1).